ST13P5 (ST13, Hsp70 interacting protein pseudogene 5)
Synonyms: formerly FAM10A5
Gene: Processed pseudogene on chromosome 11 (18,261,982 to 18,263,091, forward strand). Ensembl gene ENSG00000212789.
Subcellular location: Cytoplasm
Diseases named in the same sentence as ST13P5 in open-access papers:
ST13P5 is named in the same sentence as 2 diseases in open-access papers, as found by Europe PMC text mining. Sharing a sentence is not in itself a finding about the gene and the disease. The quoted sentences say what the papers report.
cancer (1 paper, 2025). A tumor composed of atypical neoplastic, often pleomorphic cells that invade other tissues. "These tumor suppressor genes downregulated in cancer are PDCD4-AS1, RNF40, USP4, and ST13P5." (PMID 41347211, 2025).
tumor (1 paper, 2025). "The tumor suppressors PDCD4-AS1, RNF40, USP4, and ST13P5 are good candidates for knock-in experiments to see if an increase in expression causes less or more proliferation." (PMID 41347211, 2025).